SPRY4 (sprouty RTK signaling antagonist 4)
Diseases named in the same sentence as SPRY4 in open-access papers (continued):
Sharing a sentence is not in itself a finding about the gene and the disease.
tumor (42 papers, 2011 to 2026). "Gene expression influenced by YAP1 activity in the cell models significantly overlapped with YAP1-associated genes (e.g., CYR61 and SPRY4) in published tumor data." (PMID 41681855, 2026). "As SPRY4 has been implicated as a tumor suppressor, we set out to explore the possibility that SPRY4 is mediating growth suppression selectively in the antagonistic lines." (PMID 30651601, 2019). "Additionally, SPRY4 is significantly associated with tumor size, lymphatic infiltration, and serves as an independent prognostic biomarker for PHCC." (PMID 38686189, 2024). "Spry4 has been implicated as a tumor suppressor and in modulating embryonic stem cells." (PMID 26973433, 2016). "It downregulated several potential oncogenes (e.g., AEBP1, MIAT) and genes linked to GBM proliferation and migration (e.g., SOCS2, HCP5) while modulating Wnt signaling and up-regulating tumor suppressor genes (e.g., SPRY4, BEX2)." (PMID 39874307, 2025). "Further research is ongoing to understand the expression and function of SPRY4 in specific tumor microenvironments and its potential as a therapeutic target." (PMID 38686189, 2024). "At present, researchers ardently examine the expression and functionality of SPRY4 within tumor microenvironments, striving to fathom its intricate involvement in the malignant conduct of cancer cells." (PMID 38686189, 2024). "The expression of genes measured at the end of treatment confirmed that improved tumor control is linked to a stronger inhibition of genes that report on the activity of MAPK signaling (e.g., FOSL1, DUSP6, and SPRY4)." (PMID 39199684, 2024). "In certain tumor types, the SPRY4 gene exerts its influence as a tumor suppressor, effectively quelling the malignant propensities of cancerous cells." (PMID 38686189, 2024). "3Inhibition of invasion and metastasis: SPRY4 also plays a significant role in regulating tumor cell invasion." (PMID 38686189, 2024). "SPRY4 has been validated as a tumor suppressor gene in leukemia transgenic mouse models, and its disruption leads to the development of a lethal subtype in AML." (PMID 38686189, 2024). "Knockdown of SPRY4 in MDA-MB-231 cells enhances tumor stem cell characteristics, including increased expression of CD133, CD44 subsets, and mammosphere formation." (PMID 38686189, 2024). "The relentless pursuit of utilizing SPRY4 as a promising target for anti-cancer therapeutics, aimed at enhancing tumor prognoses and surmounting drug resistance, remains an active field of investigation." (PMID 38686189, 2024). "When considering therapeutic applications, careful evaluation of the specific role of SPRY4 in different tumor or cellular contexts is necessary." (PMID 38686189, 2024). "This study showed that macrophages seem to play a central role in modulating the aggressiveness (migration and invasion) of ATC cells, unveiling SPRY4 as a possible mediator of this communication, with a tumor suppressor role." (PMID 37686663, 2023). "Sprouty4 (SPRY4) has been frequently reported as a tumor suppressor and is therefore downregulated in various cancers." (PMID 36384366, 2023). "We therefore confirmed that it is the binding of miR-18a to SPRY4 that leads to the synergistic promotion effects of miR-18a and miR-92a on the tumor growth of mice." (PMID 35484993, 2022). "Earlier was shown the tumor-suppressing role in GBM-derived cell lines of the Spry4 protein which has important functions in many receptor tyrosine kinase-mediated signal transduction cascades." (PMID 36231068, 2022). "Collectively, these findings demonstrated that miR-92a can facilitate tumor growth and metastasis through the repression of SPRY4 and the induction of EMT in vivo." (PMID 35484993, 2022).
tumor (continued). "SPRY4, as a tumor suppressor gene, was found that it has a good anti-tumor effect in vivo and in vitro and ectopic expression of SPRY4 rescued the function of miR-92a in NSCLC." (PMID 35484993, 2022). "Because the tumor-promoting effects of miR-18a were accompanied with a decrease in SPRY4 expression, we explored the mechanism by which miR-18a cooperated with miR-92a through SPRY4." (PMID 35484993, 2022). "SPRY4 is considered as a tumor suppressor, its activation reduces the proliferation and migration of GBM cells." (PMID 36354672, 2022). "The aim of the present study is to explore the role of SPRY4 during tumor progression of CRC in vivo and in vitro." (PMID 33879635, 2021). "Our results showed that both tumor size and tumor weight were reduced by Oe-SPRY4 and increased by si-SPRY4, especially, and the promotive effect of si-SPRY4 on tumor size and tumor weight was partly reversed by GSK126." (PMID 33879635, 2021). "Of these, Sprouty2 (SPRY2) and Sprouty4 (SPRY4) are downregulated compared to the corresponding non-tumor tissues, suggesting that they act as tumor suppressors in cancer via suppressing the MAPK/ERK signaling pathway." (PMID 34204242, 2021). "According to previous reports, G9a activity increases, causing an increase in global histone methylation, and further cause transcriptional repression of different tumor suppressors, including CDH1, DUSP5, SPRY4, and RUNX3." (PMID 32015216, 2020). "Compared to control tumors, SPRY4 tumors also harbored reduced Ki67, enhanced tumor cell apoptosis as shown by TUNEL staining and increased SA-ß-gal expression." (PMID 30651601, 2019). "Immunohistochemistry assay showed that SPRY4 and E-cadherin were reduced in the pLenti-miR-411 tumor tissues, whereas Ki67 and N-cadherin showed the reverse." (PMID 30390072, 2019). "Accordingly, Spry2 and/or Spry4 are shown to act as tumor-suppressors in cancer originated from, e.g., lung, liver, breast, prostate and bone." (PMID 31374860, 2019). "Taken together, SPRY4 appears to suppress in vivo tumor xenograft growth, which can be partially explained by an increase in senescence similar to the observations in vitro." (PMID 30651601, 2019). "Using the MDA-MB-231 model, we demonstrate that suppressing endogenous Spry4 increased cell growth and migration in vitro, xenograft tumor growth and metastasis in vivo, and these effects were accompanied by an increase in β3-integrin expression." (PMID 26973433, 2016). "Our studies suggest that the endogenous activity of Spry4 targets CSCs to promote the tumor suppressive phenotype." (PMID 26973433, 2016). "Given that SPRY4 is a tumor suppressor that can affect cancer cell migration/invasion and based on the observed inverse correlation with MT1-MMP, we wanted to determine the association of SPRY4 with disease progression." (PMID 26392417, 2015). "Kaplan–Meier survival analysis further showed that higher SPRY4 expression correlates with better prognosis in OS patients, suggesting that SPRY4 may function as a tumor suppressor in OS." (PMID 40416361, 2025). "In different tumor microenvironments, the role of SPRY4 may vary, and such context-dependent functions increase the complexity of cancer treatment." (PMID 38686189, 2024). "4Regulation of tumor microenvironment: SPRY4 may regulate tumor occurrence by influencing cell-cell interactions and the release of signaling molecules in the tumor microenvironment." (PMID 38686189, 2024). "first discovered that SPRY4 can regulate the characteristics of tumor stem cells." (PMID 38686189, 2024). "Moreover, as a tumor suppressor, SPRY4 can inhibit angiogenesis and increase vascular permeability in Lewis lung cancer in mice." (PMID 38686189, 2024). "In different types of tumors, SPRY4 can act as a tumor suppressor or an oncogene." (PMID 38686189, 2024). "SPRY4 also has the potential to promote proliferation in non-tumor cells." (PMID 38686189, 2024).
tumor (continued). "The regulatory role of SPRY4 in tumor development is mainly achieved through the following aspects: 1Inhibition of cell proliferation: SPRY4 inhibits tumor cell proliferation by regulating cell proliferation-related signaling pathways, such as the Ras-MAPK and PI3K-Akt pathways." (PMID 38686189, 2024). "SPRY4 overexpression inhibits tumor formation in vivo by reducing tumor size and weight." (PMID 38686189, 2024). "An in vivo research revealed that SPRY4 may influence the characteristics of cancer stem cells, as well as tumor cell migration and proliferation." (PMID 36960071, 2023). "SPRY4 can act as a tumor suppressor or an oncogene depending on human cancer." (PMID 37426199, 2023). "Moreover, the tumor xenograft method demonstrated that miR-92a facilitated tumor growth by suppressing the expression of SPRY4 and interceding Epithelial-Mesenchymal Transition (EMT) in vivo." (PMID 37986065, 2023). "We identified SPRY4 as a crucial mediator in this interplay, being a candidate tumor suppressor gene in this context, which may be useful to disclose new processes related to ATC aggressiveness that can lead to future therapeutic options." (PMID 37686663, 2023). "In GIST, positive expression of Stem Cell Growth Factor (SCGF) has been associated with response to the tyrosine kinase inhibitor imatinib, and exosomal expression of proteins Sprouty homolog 4 (SPRY4) and tyrosine protein kinase KIT have been associated with increased risk of tumor progression." (PMID 37197427, 2023). "In both contexts, SPRY4 seems to be playing a tumor suppressor role." (PMID 37686663, 2023). "In addition, the expression level of miR-92a was downregulated significantly in the tumor tissues of the pLenti-miR-92a+AntagomiR-18a and pLenti-miR-18a+AntagomiR-18a groups, accompanied by the upregulated expression of SPRY4." (PMID 35484993, 2022). "As for the synergistic effects between miR-92a and miR-18a, we found that both miR-18a and miR-92a can target SPRY4 through the dual-luciferase reporter assay, so it proves that miR-18a and miR-92a may play tumor-promoting roles by targeting SPRY4 commonly." (PMID 35484993, 2022). "Furthermore, the tumor xenograft assay showed that miR-92a facilitated tumor growth by inhibiting the expression of SPRY4 and mediating Epithelial-Mesenchymal Transition (EMT) in vivo." (PMID 35484993, 2022). "SPRY4 as a classic tumor suppressor has been confirmed in many researches." (PMID 35484993, 2022). "However, the expression of SPRY4 has little relationship with the pathological stage, gender, or tumor size." (PMID 35484993, 2022). "Our previous study has proved that SPRY4 could serve as a direct target of miR-411 and play a tumor suppressor role in NSCLC." (PMID 35484993, 2022). "SPRY4 has been reported to act as a tumor suppressor gene in various tumors." (PMID 33879635, 2021). "Additionally, Spry4 is a well-documented tumor suppressor in tumors originating from e.g., lung, breast, and brain." (PMID 34769378, 2021). "Even though mounting evidence has highlighted the SPRY4 functions as tumor suppressor, the effects and the mechanism of SPRY4 in regulating CRC progression remain unclear." (PMID 33879635, 2021). "Thus, SPRY4 plays a dual role in human cancers and the function of SPRY4 often varies among different tumor types." (PMID 33879635, 2021). "We demonstrated that differential expression modality between cancer cells and normal cells in SPRY4, which hinted that SPRY4 might serve as a tumor suppressor gene that negatively regulates tumor development." (PMID 33879635, 2021). "Additionally, Spry4 can fulfill a tumor-suppressing role by interfering with angiogenic signals and thereby inhibits neovascularization and tumor growth." (PMID 31374860, 2019). "Collectively, these findings demonstrated that miR-411-5p/3p could promote tumor growth through the repression of SPRY4 and might induce tumor metastasis." (PMID 30390072, 2019).
tumor (continued). "Finally, suppressing Spry4 increased the potency of MDA-MB-231 cell tumor initiation, a feature attributed to cancer stem cells." (PMID 26973433, 2016). "Few other studies have showed SPRY4 tumor suppressor function." (PMID 26392417, 2015). "To test whether the in vitro features of Spry4 knockdown cells are maintained in vivo, we performed orthotopic xenograft analysis to test if knockdown of Spry4 affects the tumor formation by injecting 1 × 106 NT or S4kd#1 cells into the mammary fat pads of immunodeficient NOD/SCID mice." (PMID 26973433, 2016). "The mechanism of Spry4 in regulating tumor cell migration remains unclear." (PMID 26973433, 2016). "When SPRY4 is expressed at high levels, it blocks ERK1/2 phosphorylation, leading to reduced tumor proliferation and inducing G1-phase arrest." (PMID 40723336, 2025). "We demonstrated that SPRY4 undergoes a dynamic palmitoylation cycle regulated by ZDHHC7 and PPT1, which modulates MAPK signaling and subsequently affects tumor cell proliferation, migration, apoptosis, and drug resistance." (PMID 40416361, 2025). "Intron two of the SPRY4 gene generates SPRY4 intronic transcript 1 (SPRY4-IT1), a molecule that assumes the role of either a tumor suppressor or an oncogenic factor in various cancer types." (PMID 38434620, 2024). "SPRY4 can suppress the activity of matrix metalloproteinase 9, increase the expression of TIMP1 and CD82, and inhibit tumor cell invasion and metastasis." (PMID 38686189, 2024). "These research findings emphasize the complex role of SPRY4 in the development of NSCLC and how it interacts with tumor biology through different signaling pathways and molecular modulators." (PMID 38686189, 2024). "Mechanistically, in the nucleus, CCAT1 can act as a scaffold for two distinct histone methylation complexes, leading to the repression of sprouty RTK signaling antagonist 4 (SPRY4), which is considered a tumor suppressor gene." (PMID 38540273, 2024). "Currently, only a tumor suppressor function for SPRY4 has been posited in CRC, where SPRY4 mRNA underexpression was reported in a limited number of CRC patients." (PMID 36384366, 2023). "We next examined the degree of MAPK pathway inhibition after treatment in tumor cells using an MAPK gene expression signature score based on changes in the MAPK-regulated transcripts (DUSP6, ETV4, ETV5 and SPRY4) in tumor epithelial cells." (PMID 36702949, 2023). "SPRY4 is a possible modulator of macrophage–ATC cell communication, with a tumor suppressor role relevant for therapeutic purposes." (PMID 37686663, 2023). "In BRAF or RAS mutant tumor cells, DUSP4, DUSP6, SPRY2, and SPRY4 tend to be highly expressed, allowing tumors to evade regular MAPK signaling pathway feedback." (PMID 36437939, 2022). "The high SPRY4 expression often impedes cell growth of NSCLC and induces a reversal of EMT characteristic of tumor cells." (PMID 30390072, 2019). "There are a further eight tumor-suppressor genes (DLEU2, CDKN2C, SPRY4, UBE2QL1, LIN9, TFPI2, LRIG3, DUSP1) and six genes serve as both oncogenes and tumor-suppressor genes (FOXO1, CAV1, KLF6, CDK6, PLK1, CTGF)." (PMID 30563222, 2018). "Other potential tumor suppressor genes downregulated by G9a were GADD34 (PPP1R15A), a growth arrest and DNA damage-induced protein and Sprouty4 (SPRY4), an inhibitor of the Ras/MAPK signaling cascade." (PMID 25115793, 2014). "Conversely, in pCCA subtype, it has been shown that Sprouty RTK signaling antagonist 4 (SPRY4) is significantly downregulated in tumor tissue compared to adjacent non-tumor tissue, and that its low expression correlates with worse prognosis." (PMID 40723336, 2025). "SPRY4, as a negative regulator of MAPK activation, its ectopic expression has been shown to inhibit proliferation and migration in GBM cells, suggesting its role as a tumor suppressor." (PMID 39874307, 2025).
tumor (continued). "In TGCT cell lines (833 K and NT2-D1), reducing SPRY4 expression through siRNA leads to decreased activation of the PI3K/Akt signaling pathway, resulting in reduced cell growth, migration, and invasion, thereby promoting tumor development." (PMID 38686189, 2024). "The results indicate that SPRY4 methylation status was independent of tumor grades and differentiation status in a small subset analysed." (PMID 36384366, 2023). "Furthermore, SPRY4 proteins, compacted into nano-sized vesicles, target and reprogram neighbouring cells when released as circulating exosomes from GIST-derived tumor cells." (PMID 36384366, 2023). "SPRY4 is epigenetically upregulated in CRC by promoter hypomethylation and hypermethylation within the gene body that warrants future investigation of atypical roles of this established tumor suppressor." (PMID 36384366, 2023). "The authors conclude that expression of SPRY4 and KIT may represent markers of tumor progression and could be predictive of imatinib therapeutic response." (PMID 37197427, 2023). "Collectively, this study found that SPRY4 might act as an anti-tumor gene in CRC and SPRY4 exerted a suppressive effect on CRC progression via the inhibition of EZH2." (PMID 33879635, 2021). "The micro RNA miR-411-5p/3p is significantly upregulated in human NSCLC tissues and cell lines, and the overexpression of miR-411-5p/3p can inhibit the expression of SPRY4 and TXNIP, which in turn promote tumor proliferation and migration, preventing apoptosis in NSCLC cell lines." (PMID 33194655, 2020). "Moreover, miR-411-5p/3p expression was significantly upregulated, and SPRY4 and TXNIP protein expression was downregulated in tumor tissues of the pLenti-miR-411 group." (PMID 30390072, 2019). "Furthermore, our findings showed that miR-411-5p/3p promoted lung tumor growth in vivo, decreased SPRY4 expression dramatically, and induced EGFR, AKT signaling activation, as well as epithelial–mesenchymal transition (EMT) simultaneously in tumor tissues." (PMID 30390072, 2019). "We identified the tumor suppressor gene SPRY4 as a new transcriptional target of MT1-MMP that is negatively regulated by the protease." (PMID 26392417, 2015). "Five genes with tumor suppressing properties, i.e. SPRY4 (Sprouty homolog 4), DUSP4 and DUSP6 (dual-specificity phosphatases 4 and 6), LRIG1 (Leucine-rich repeats and Ig-like domains 1) and PHLDA1 (Pleckstrin homology-like domain family A, member 1), were upregulated by KGF (1.5–2.1 fold)." (PMID 22427941, 2012). "In the present study, we put forward that SPRY4 could be a key mediator for the observed differences in the phenotypes of T235 (BRAF mutant) and C3948 (BRAF wild type) cell lines, under macrophage modulation in the tumor microenvironment." (PMID 37686663, 2023). "Moreover, SPRY4 regulates various signals negatively in angiogenesis, selectively suppressing angiogenic signals independent of Ras in the tumor microenvironment." (PMID 30390072, 2019). "We demonstrate that Spry4 knockdown MDA-MB-231 cells led to enhancement of CSC features, including increased CD133+CD44+ subpopulation and mammosphere formation, decreased sensitivity to Paclitaxel treatment in vitro, and increased capacity for xenograft tumor initiation in vivo." (PMID 26973433, 2016). "The reciprocal mRNA expression patterns of G9a versus DUSP5, SPRY4, PPP1R15A in datasets as well as the protein expression patterns of G9a versus Sprouty4 and GADD34 in clinical samples strengthen the correlation between G9a and these tumor suppressive genes in OCa progression." (PMID 25115793, 2014).